RUNX2 (RUNX family transcription factor 2)
Diseases named in the same sentence as RUNX2 in open-access papers (continued):
Sharing a sentence is not in itself a finding about the gene and the disease.
tumor (continued). "Moreover, according to our previous findings, we observed a significant correlation between RAIN and RUNX2 expression levels in both primary tumor (Spearman correlation (R) = 0.53, p = 0.003) and metastatic samples (Spearman correlation (R) = 0.42, p = 0.025)." (PMID 39271656, 2024). "In this framework, the Runt-related transcription factor 2 (RUNX2) and the C-X-C motif chemokine receptor 4 (CXCR4) have emerged as proteins of interest, being associated with the migration, invasion, and metastasis of tumour cells." (PMID 38474372, 2024). "Inhibition of Runx2 can directly affect tumor cells or disrupt the tumor microenvironment." (PMID 39595568, 2024). "In addition, miR-30a not only acted as a tumor suppressor, but also as a new therapeutic target for osteolysis by targeting RUNX2 mRNA, providing more possibilities to regress GCT progression in patients." (PMID 37057210, 2023). "Furthermore, knocking out E-cadherin restored the luciferase activity of these cells in Runx2-expressed tumor cells." (PMID 37150786, 2023). "RUNX2 was irrelevant to gender, age, tumor size, and tumor stage." (PMID 36200301, 2023). "The heterogenous expression of RUNX2 within GC tumours of the bone in our study may be due to an unequal distribution of mature osteoclast-like GC, and areas of osteolysis driven by RUNX2." (PMID 37509363, 2023). "In line with this, the binding of YAP with RUNX2 was upregulated in the stiff tumor cells." (PMID 37614365, 2023). "In contrast, Runx2 knockout induced delay in tumor onset but more rapid growth after onset in vivo." (PMID 37212282, 2023). "And the protein expression of RUNX2 and β‐catenin was upregulated in ccRCC tumor tissues." (PMID 36200301, 2023). "RUNX2 may act as a tumor suppressor or an oncoprotein, depending on its expression, its environment, and its regulation." (PMID 37370857, 2023). "RUNX2 has been shown to be highly expressed in GC tumours of the bone." (PMID 37509363, 2023). "Indeed, reduced in vitro infection and viral spread, as well as delayed tumor activation in a MYC/Runx2 mouse model using replication-competent recombinant MuLV lacking a functional (i.e., BET protein-binding) ET domain-binding motif, have been reported." (PMID 37766260, 2023). "However, it has also been demonstrated that RUNX2 is involved in tumor cells invasion, especially in bone metastases and in the development of malignant tumors." (PMID 37316755, 2023). "Recently, the correlation between MAPKs and RUNX2 has been recorded in different tumours." (PMID 37525479, 2023). "In this case, PVT1 was able to directly interact with miR‐30d‐5p, resulting in a competitive binding that decreased miR‐30d‐5p abundance and relieved the repression mediated by this miRNA on the downstream target RUNX2, an oncogene related to tumor growth and metastasis." (PMID 36366788, 2023). "Despite its conventional role as a tumor suppressor, recent data suggests that RUNX2 may have a direct involvement in promoting neoplasia, especially in prostate and breast malignancies." (PMID 37370857, 2023). "Moreover, evidence has confirmed that RUNX2 expression and activity in MM cells sustain angiogenesis, cell survival and tumor progression, leading to poor prognosis." (PMID 36077711, 2022). "Runx2 and TGFβ assist tumor progression, and Snail is involved in EMT." (PMID 35547745, 2022). "RUNX2 has been recognized as the basic transcription factor for various physiological development (e.g., skeletal and osteogenic development), and the concomitant pathological processes including cancer development and tumor bone metastasis." (PMID 36483054, 2022). "Furthermore, the RUNX2/NuRD(MTA1)/CRL4B complex contributed to the epigenetic silencing of tumor suppressors." (PMID 35534547, 2022). "A review reported that mutual activation of the PI3K/Akt pathway and RUNX2 may be one of the main drivers of tumor progression or migration." (PMID 36686663, 2022).
tumor (continued). "As for RUNX2, based on its general metastasis-enhancing functions, it could be a promising target for preventing tumor metastasis and predicting patient outcomes." (PMID 36429115, 2022). "Overexpression of Runx2 reverses the tumor-suppressive effect of miR-23a-3p." (PMID 35342401, 2022). "In addition, we demonstrated that GDF10 promotes the functional transformation of normal human NF into CAF by LOC100506114 binding to transcription factor RUNX2, to support tumor cell growth, invasion and metastasis." (PMID 33657265, 2022). "Indeed, RUNX2 knockdown in MM cells significantly reduces different patterns of cytokines, chemokines and growth factors involved in tumor progression and bone metastasis, thus counteracting MMABD progression." (PMID 36077711, 2022). "As such, RUNX2 downregulation was shown to inhibit tumor growth and bone metastasis in Pca." (PMID 35406450, 2022). "Moreover, RUNX2 transactivates genes related to tumor progression, invasion, and metastasis, including survivin, MMP-2, MMP-9, and VEGF." (PMID 36231060, 2022). "The role of RUNX2 in tumour metastasis, development and progression has been widely reported." (PMID 36264762, 2022). "Recent studies found RUNX2 was overexpressed in several tumor tissues and may play a vital role in tumor initiation, progression, invasion and metastasis." (PMID 34606473, 2021). "Furthermore, in a mouse model, mice inoculated with Runx2-silenced EO771 cells exhibited reduced tumor weights." (PMID 34230453, 2021). "Therefore, dysregulation of Runx2 modulates tumor cell proliferation and metastasis, and revealing the underlying mechanism is urgent in the future development of individual treatments against different types of cancer." (PMID 33767130, 2021). "Moreover, RUNX2 expression was markedly elevated in tumor tissues formed by MDA‐PCa‐2b cells overexpressing NEAT1." (PMID 34459124, 2021). "Furthermore, runt related transcription factor 2 (RUNX2) is a member of the RUNX family that activates genes associated with tumorigenesis and metastasis, promoting tumor cell invasion in cancer." (PMID 34248996, 2021). "However, the loss of TCF7L2 promotes migration and the invasion of human CRC by suppressing the expression of pro-oncogenic transcription factor RUNX2 and cell adhesion molecules, supporting tumour-suppressive functions." (PMID 35860598, 2021). "In addition, the overexpression of Lrp5 elevated Snail, MMP9, Runx2, and TGFβ and promoted the proliferation and invasion of 4T1Br tumor cells." (PMID 34031366, 2021). "To evaluate the expression patterns of genes involved in tumor-induced osteolysis with respect to α2β1 integrin, we performed qPCR and western blot analysis for PTHrP and Gli2 and TGFβrII and RUNX2 in MDA-Ctrl or MDA-OEα2 cells, and MDA-Parental or MDA-Bone cells." (PMID 34199096, 2021). "MALAT1 can promote metastasis of COAD via RUNX2 as a survival factor in tumor cells." (PMID 32727450, 2020). "Indeed, both SOX9 and RUNX2 can act as oncogenes or tumor suppressors in a context-dependent manner—their expression is characteristic for cancer stem-like cells (CSCs) and they are involved in metastasis and chemoresistance." (PMID 33287223, 2020). "Runx2 was up-regulated in HCC compared to adjacent non-tumor tissues (P < 0.05)." (PMID 32913476, 2020). "Such a dual functionality of RUNX2 thus suggests that RUNX2 protein could act as either a tumor suppressor or an oncoprotein." (PMID 32695811, 2020).
tumor (continued). "Based on our findings, we speculate that the expression of RUNX2 in GC tissue changes with the degree of tumor malignancy, and its effect on FN1 also changes, and with a high degree of malignancy, the two genes are negatively correlated." (PMID 33313404, 2020). "Runx2 also acts to diversify functions in various other tissues, Runx2 regulates vascular calcification in vessels, and it might constitute a major driving force in tumor progression and aggressiveness." (PMID 32596356, 2020). "RUNX2 has been shown to be involved in many molecular mechanisms of tumor progression." (PMID 33313404, 2020). "As a proof-of-principle, we here generated four novel R26 KI mice that enable conditional overexpression of 3 putative oncogenes (Jarid2, Runx2, MN1) and one dominant negative allele of a tumour suppressor (dnETV6), which all have been previously associated with the pathobiology of human leukemia." (PMID 31332244, 2019). "Restoration of Runx2 in miR-196a-knockdown HCC reverted tumor phenotypes." (PMID 31614906, 2019). "This suggests that HOXA9 could be linked to the calcification and tumour invasion of PTC, which is both independent and dependent of RUNX2." (PMID 31043660, 2019). "Similarly, there is evidence that miR-135 and miR-203 can impact tumor growth in the bone microenvironment, through influencing RUNX2 protein levels." (PMID 31603918, 2019). "Indeed several studies reported the over-expression of RUNX2 in tumor derived from epithelial tissues, including: thyroid, breast, pancreas, prostate, lung, melanoma, glioma, colorectal and osteosarcoma." (PMID 31395086, 2019). "Studies in tumor cells have demonstrated that Runx2 binds to α-tubulin via its amino terminus, and that these interactions with tubulin are necessary for the nuclear export of Runx2 and sequestration of the transcription factor in the cytoplasm in these cells." (PMID 30581820, 2018). "In addition to osteogenesis-related genes, RUNX2 has an ability to transactivate its downstream target genes involved in tumor progression, invasion and metastasis such as MMP9, MMP13, VEGF, survivin, IL-8 and TGFβR." (PMID 29558908, 2018). "In addition to its pro-osteogenic role, a growing body of evidence strongly suggests that RUNX2 plays a vital role in tumor initiation, progression, invasion and metastasis." (PMID 29558908, 2018). "Additionally, altered RUNX2 is involved in unchecked pathways promoting tumor progression, Epithelial Mesenchymal Transition (EMT), and metastasis." (PMID 30463392, 2018). "Importantly, XRK3F2, an inhibitor of the p62-ZZ domain, blunted MM-induced Runx2 suppression in vitro, and induced new bone formation and remodeling in the presence of tumor in vivo." (PMID 30008697, 2018). "However, in contrast to RUNX2, the expression, regulation and function of the defining osteoblastic enzyme alkaline phosphatase in tumour cells is poorly understood." (PMID 28006818, 2017). "Runx2 could be a potential target for tumor cells prone to spread to distant organs via invasion and metastasis." (PMID 28264434, 2017). "The in vitro data showed that Runx2 plays an important role in tumor cell invasion and migration." (PMID 28264434, 2017). "Moreover, the robust increase of RUNX2-positive osteoblasts observed in rat tibia in the vicinity of Dunning G cells indicates tumor cell dependent induction of osteoblast differentiation and increased bone formation." (PMID 28447314, 2017). "Runx2 expression was silenced by RNAi method to detect whether Runx2 was involved in the anti-tumour effect of miR-302b." (PMID 29042587, 2017). "However, RUNX2 was reported as only weakly expressed in GC tissue and has tumor suppressor activity in GCs." (PMID 27007162, 2016). "miR-221-3p, an established PCa tumor suppressor, uniquely targets Runx2." (PMID 27634876, 2016). "However, some important questions remain unanswered: How does AKT participate in the switch of RUNX2 from a tumor suppressor to a pro-oncogenic factor at advanced stages of cancer?" (PMID 26204939, 2015).
tumor (continued). "While E-Cadherin is a defined tumor suppressor that is inactivated by transcriptional or promoter methylation mechanisms, the shed soluble ectodomain (sE-Cad) exhibits oncogenic activity and its levels increased in RUNX2+ cells." (PMID 26320173, 2015). "The involvement of RUNX2 in tumor development, progression and metastasis is largely documented." (PMID 26204939, 2015). "This mutual activation in the context of cancer cells exhibiting constitutive AKT activation and high levels of RUNX2 might constitute a major driving force in tumor progression and aggressiveness." (PMID 26204939, 2015). "Furthermore, miR-135 and miR-203 reduce tumor growth and metastasis of MD-MB-231 cells to the bones by targeting the runt-related transcription factor 2 (Runx2)." (PMID 26377202, 2015). "It was suggested that RUNX2 is expressed early during cancer progression and might be responsible for early events of tumor development." (PMID 26404249, 2015). "In addition to the interdependence of RUNX2 and the TGFβ signaling pathway during the EMT process, the RUNX2-SMADs partnership is central for tumor growth, metastasis and bone disease." (PMID 26204939, 2015). "Interestingly, the expression of extracellular matrix genes laminin and collagen I (a RUNX2 target) were increased while expression of the anti-tumor and anti-angiogenic matrix protein thrombospondin was repressed." (PMID 26320173, 2015). "In addition, the pro-angiogenic effects of RUNX2 are highly suggestive of RUNX2 as a major player in tumor promotion." (PMID 26204939, 2015). "We showed previously that tumour onset could be accelerated by retroviral infection and a RIM screen identified a number of candidate third hit genes, including Pim1, a gene that accelerates tumour onset when combined with MYC/Runx2 in the germ-line." (PMID 24586197, 2014). "Moreover, in non-small cell lung cancer-patients, higher RUNX2 expression was significantly correlated with tumor progression and metastasis." (PMID 25266482, 2014). "The tumor suppressor role of RUNX2 andRUNX3 mainly relates to the antagonism between RUNX2/3 and the cancer-promoting programof ER signaling, whereas the tumor suppressor role of RUNX1 largely correlates to itsability to positively regulate the tumor-suppression program of ER signaling." (PMID 25415051, 2014). "This indicates a different regulatory role of Runx2 when ectopically expressed in tumor cells." (PMID 24292404, 2014). "Thus, our data confirm recent findings suggesting that RUNX2 promotes tumor and cancer cell growth and/or invasion/metastasis." (PMID 24124450, 2013). "Compared to normal human osteoblasts, every tumour specimen had higher RUNX2 mRNA expression." (PMID 21197465, 2011). "We therefore hypothesized that gene(s) stimulated by Runx2 and inhibited by E2 may contribute to manifestations of the pro-metastatic or tumor suppressor functions of Runx2 and E2, respectively." (PMID 22151997, 2011). "Clearly, the prodifferentiation and tumour suppressor function of RUNX2 has potential for deregulation, in that MSCs committed to the osteoblast lineage could be stalled in their differentiation before development of the mature osteoblast phenotype." (PMID 21197465, 2011). "However, when the cells were treated with adenovirus expressing Runx2 (even in the presence of osteogenic BMPs), the tumor growth was significantly inhibited, and these cells underwent terminal differentiation and apoptosis." (PMID 21437219, 2011). "Since Runx2 is a DNA-binding transcription factor that interacts with the TGFβ/Smad family of transcriptional modulators to stimulate cell proliferation and tumor progression, we looked for the signs of LGD1069 affecting the phosphorylation of Smads in HUVECs simulated by VEGF." (PMID 21649908, 2011).
tumor (continued). "Thus, Runx2 and E2 signaling play dual roles in BCa, with each functioning to either promote or suppress tumor progression." (PMID 22151997, 2011). "Our results may be reflective of either increased levels of gene expression in individual tumor cells during disease progression, or alternatively an increased proportion of cell lineages with RUNX2 expression in these genetically highly heterogenous cells." (PMID 20465837, 2010). "It is therefore tempting to speculate that Runx2 – induced via paracrine effects of the activated stroma – functions as tumour suppressive." (PMID 17876328, 2007). "If a TI calf developed cancer, it is possible that other epigenetic alterations could enhance the development and metastasis of cancer, as is demonstrated by predicted activation of the transcriptional regulation by RUNX2 pathway which can promote tumor growth and metastasis." (PMID 40316897, 2025). "Furthermore, RUNX2 controls the expression of proteins that confer radioresistance to tumour cells." (PMID 40806771, 2025). "In LUAD, a cigarette extract was found to promote the expression of RUNX2, which then induced the upregulation of stemness markers in airway epithelial cells (AECs), leading to increased migration, invasion, and tumorsphere formation by tumor stem cells at the molecular level in AECs." (PMID 38430423, 2024). "Remarkably, the RUNX2 gene has been discovered by next generation sequencing to be one of the fusion partners of the gene encoding ubiquitin-specific peptidase 6 (USP6), possibly contributing to the osteoblastic as well as osteolytic features of this neoplasia." (PMID 37509363, 2023). "However, RUNX2-expression reported in the literature is mainly localised in the mononuclear stromal cells; in this localisation, the transcription factor has been proposed to play a role in the osteolytic activity within GC tumours of the bone." (PMID 37509363, 2023). "Experiments on HCC cell lines revealed that RUNX2 is associated with EMT and VM processes by regulating the expression of adhesion molecules such as VE-cadherin and galectin-3, which indirectly contribute to tumour cell migration and enhanced metastatic potential." (PMID 37759525, 2023). "However, the relationship between RUNX2 and tumor immune microenvironment in BLCA was largely unknown." (PMID 37519798, 2023). "Furthermore, RUNX2 activity in MM cells sustains angiogenesis, cell survival and tumor progression." (PMID 36077711, 2022). "Moreover, Runx2 is expressed in many cancer cells promoting tumor progression." (PMID 34445164, 2021). "In addition, we examined the potential involvement of Runx2 in tumor progression." (PMID 34230453, 2021). "However, further validation is required to establish whether the upregulation of FGF2 and Runx2 is linked to BMP2 expression in EBV-associated NPC and other virus-associated tumours." (PMID 32708289, 2020). "Moreover, exogenous Runx2 expression could inhibit the tumor growth of OS cells, which suggested that OS cells may be obstructed in undergoing terminal differentiation by impairments in the osteogenic pathway." (PMID 24762763, 2014). "A role for RUNX2 in promoting crosstalk between CaP and osteoblasts/osteoclasts in bone metastases has been known for some time, especially in the context of being an inducer of genes regulating extracellular matrix proteolysis, osteolysis, and tumor cell epithelial-to-mesenchymal transition." (PMID 24983969, 2014). "We speculate that miR-27a and miR-24 may serve at a ‘standby state’, which means they are ready for the manipulation by different cellular factors, as GATA-1 in erythropoiesis, c-MYC in tumour metastasis, Runx2 in osteoblast differentiation and PU.1 in B-cell development." (PMID 24049083, 2014).